FABP3 (fatty acid binding protein 3)
Diseases named in the same sentence as FABP3 in open-access papers (continued):
Sharing a sentence is not in itself a finding about the gene and the disease.
cardiac hypertrophy (7 papers, 2013 to 2025). "Altogether, we concluded that FABP3 deficiency promoted cardiac hypertrophy after TAC operations." (PMID 34458345, 2021). "The deficiency in Fabp3 leads to reduced fatty acid oxidation (FAO), increased glycolysis, and abnormal lipid accumulation, thereby exacerbating cardiac hypertrophy and dysfunction induced by aortic dissection." (PMID 40259242, 2025). "In the FABP3-deficient mouse, a change in fuel utilization from LCFA to glucose, accompanied by decreased exercise tolerance and cardiac hypertrophy, were observed." (PMID 37207357, 2023). "We aimed to determine the metabolic roles of fatty acid binding protein 3 (FABP3) on transverse aortic constriction (TAC)-induced cardiac hypertrophy." (PMID 34458345, 2021). "Then, by using TAC operation to induce cardiac hypertrophy in vivo and neurohormonal stimuli (NE or Ang II) in vitro, we observed increased FABP3 expression after TAC operations and after neurohormonal stimuli." (PMID 34458345, 2021). "Herein, we observed an indispensable role of FABP3 in the incidence and advance of cardiac hypertrophy." (PMID 34458345, 2021). "Our findings indicate that Fabp3-defect exacerbates cardiac hypertrophy and heart dysfunction, resulting in defective FAO, and increased glycolysis by impairing the PPARα signaling pathway." (PMID 34458345, 2021). "In conclusion, in the present study, we provide novel insights into the regulatory role of FABP3 on cellular metabolism following TAC-induced cardiac hypertrophy." (PMID 34458345, 2021). "Altogether, these data illustrate that FABP3 participates in cardiac hypertrophy by synergistically activating Mlycd and Cpt1b and repressing Gck and Acaca via PPARα." (PMID 34458345, 2021). "In conclusion, we have provided a novel perspective into the relationship between FABP3 with cardiac hypertrophy and fuel preference." (PMID 34458345, 2021). "Next, we sought to explore the mechanism through which Fabp3 mediates metabolic derangement during cardiac hypertrophy." (PMID 34458345, 2021). "Altogether, these FABP3 loss- and gain-of-function results corroborate with in vivo phenotypes and reveal the important role of FABP3 in the development of cardiac hypertrophy." (PMID 34458345, 2021). "Based on the expression profile and metabolic effects, the interactive effects of FABP3 and PPARα in cellular metabolism and cardiac hypertrophy were explored in this article." (PMID 34458345, 2021). "Finally, to demonstrate the requirement of PPARα in FABP3 mediated cardiac hypertrophy, PPARα was knocked down using siRNA methods." (PMID 34458345, 2021). "Interestingly, compared with the vehicle group, fenofibrate treatment significantly rescued cardiac hypertrophy in WT and Fabp3-KO mice." (PMID 34458345, 2021). "Moreover, etomoxir treatment would reverse the protective effects of FABP3 on cardiac hypertrophy and upregulated the mRNA expression of Bnp and Anp." (PMID 34458345, 2021). "Here, our in vivo and in vitro results reveal the potential mechanism of the FABP3-mediated PPARα pathway in cardiac hypertrophy and in FAO/glycolysis balance by directly binding to PPARα, promoting its stability, and underpinning its transactivation in Mlycd and Gck." (PMID 34458345, 2021). "To explore the mechanism through which FABP3 regulates cardiac hypertrophy, we collected F3-KO or WT hearts at 1-week post-sham or -TAC operation for RNA-seq analysis and liquid chromatography–mass spectrometry (LC-MS) analysis to determine differential genes and metabolites." (PMID 34458345, 2021). "Additionally, FABP3 has been described in the context of cardiac hypertrophy, with a positive relationship being described between cellular and circulating levels of FABP3 and cardiac hypertrophy in patients and mice." (PMID 34458345, 2021). "However, the mechanism through which FABP3 affects cellular metabolic homeostasis and advances of cardiac hypertrophy remains poorly understood." (PMID 34458345, 2021).
cardiac hypertrophy (continued). "Notably, cardiac FABP3 was completely abolished using this knockout strategy, which allowed for a direct examination for FABP3 on cardiac hypertrophy." (PMID 34458345, 2021). "Additionally, treatment with the PPARα agonist, fenofibrate, effectively repressed Fabp3-KO induced cardiac hypertrophy, highlighting a potential clinical value of hypertrophic treatment by targeting cardiac energy metabolism." (PMID 34458345, 2021). "Meanwhile, targeting FABP3 with an agonist may represent an attractive approach to alleviate deranged metabolic milieu in cardiac hypertrophy and achieve the goal of improved heart function." (PMID 34458345, 2021). "Furthermore, Fabp3 mediated the PPARα protein levels by directly binding to PPARα and preventing its degradation and underpinning its transactivation on Mlycd and Gck, which underscores the pivotal metabolic role of PPARα in FABP3-mediated cardiac hypertrophy." (PMID 34458345, 2021). "Furthermore, the agonist of PPARα, fenofibrate, attenuated TAC-induced cardiac hypertrophy in both wild-type (WT) and Fabp3-null mice." (PMID 34458345, 2021). "Fabp3-defect exacerbates cardiac hypertrophy and heart dysfunction, but over-expression of Fabp3 can up-regulate the phosphorylation of the MAPK signaling pathway and decrease phosphorylated Akt levels, which may account for the augmentation of apoptosis and remodeling after myocardial infarction." (PMID 37355664, 2023). "Notably, Fabp3 ablation aggravated TAC-induced cardiac hypertrophy and cardiac dysfunction." (PMID 34458345, 2021). "Collectively, these results demonstrate an important role of the FABP3-PPARα pathway on fuel preference and cardiac hypertrophy, while treatment with fenofibrate may reverse hypertrophy, suggesting the potential clinical value for fenofibrate in hypertrophic treatment." (PMID 34458345, 2021). "Taken together, we showed that Fabp3-null contributes to defective FAO and increased lipid biogenesis and toxic lipid accumulation after cardiac hypertrophy." (PMID 34458345, 2021). "To examine the effects of FABP3 on cardiac hypertrophy, we generated F3-KO mice using CRISPR/Cas9, and these Fabp3-null mice were viable and fertile." (PMID 34458345, 2021). "We next sought to determine whether activating PPARα may rescue the pro-hypertrophic effects of Fabp3 defect after TAC operation and search for clinical benefits on the treatment of cardiac hypertrophy." (PMID 34458345, 2021). "Consistently, we showed that FABP3 was increased in response to hypertrophic stimulations in vivo and in vitro to modulate cardiac metabolic homeostasis, especially the FAO and glucose oxidation processes under cardiac hypertrophy, a disease condition with higher energy demands." (PMID 34458345, 2021). "As regard the pleiotropic effects of PPARα on inhibiting glucose oxidation, while activating FAO, we aimed to determine whether FABP3 interacts with PPARα and modulates its transcriptional capacities on FAO/glycolysis genes, and further is involved in the advance of cardiac hypertrophy." (PMID 34458345, 2021). "Importantly, the compounds described herein weakly interact with FABP3, which may be advantageous as previous work has shown that mice lacking FABP3 develop age-dependent cardiac hypertrophy." (PMID 24705380, 2014).
type 2 diabetes mellitus (7 papers, 2018 to 2024). A type of diabetes mellitus that is characterized by insulin resistance or desensitization and increased blood glucose levels. "FABP3 inhibitors may be useful to prevent the deleterious effects of FA binding and lipid accumulation in pancreatic islets resulting in ß-cell loss and contributing lastly to the pathogenesis of type 2 diabetes." (PMID 38960943, 2024).
endothelial dysfunction (6 papers, 2020 to 2025). In vascular diseases, endothelial dysfunction is a systemic pathological state of the endothelium (the inner lining of blood vessels) and can be broadly defined as an imbalance between vasodilating and vasoconstricting substances produced by (or acting on) the endothelium. "Recent studies showed that the loss of FABP3 improves lipopolysaccharide-induced inflammation and endothelial dysfunction, also supporting our findings." (PMID 38218337, 2024). "Together, these findings suggest that gain-of endothelial FABP3 exacerbates, whereas loss-of endothelial FABP3 inhibits LPS-induced endothelial dysfunction by promoting cell survival and anti-inflammatory and pro-angiogenic signaling." (PMID 36681124, 2023). "Overall, these data indicate that loss of FABP3 protects against LPS-induced endothelial dysfunction by restoring angiogenic, migratory, and proliferative potential and by inhibiting LPS-induced apoptosis of endothelial cells." (PMID 36681124, 2023). "In summary, our data demonstrate that FABP3 is expressed in endothelial cells and that loss of endothelial FABP3 inhibits LPS-induced endothelial dysfunction by modulating cell survival and inflammatory and angiogenic signaling pathways." (PMID 36681124, 2023). "Taken together, these data indicate that FABP3 exposure exacerbates LPS-induced inflammation in vitro and may cause endothelial dysfunction in vivo in endothelial cells." (PMID 36681124, 2023). "Maximum but similar FABP3 expression was observed for 100 and 200 ng/ml of LPS, and accordingly, 100 ng/ml was chosen to be the experimental dose to evaluate the effect of loss of FABP3 on LPS-induced endothelial dysfunction." (PMID 36681124, 2023). "Furthermore, loss-of-endothelial FABP3 inhibits LPS-induced endothelial dysfunction by promoting cell survival and anti-inflammatory and pro-angiogenic pathways." (PMID 36681124, 2023). "Others have demonstrated that FABP3 is associated with endothelial dysfunction, which may result from PAD." (PMID 35795372, 2022). "Hereby, recent animal data point toward a critical role of FABP3 for muscle atrophy and endothelial dysfunction." (PMID 38982001, 2025). "Inhibition of FABP3 or ferroptosis can restore PGPC-impaired endothelial dysfunction." (PMID 38218337, 2024). "In summary, the oxidized phospholipid component PGPC can increase FABP3 expression via the CD36 receptor to induce EC ferroptosis, resulting in endothelial dysfunction." (PMID 38218337, 2024).
hyperlipidemia (6 papers, 2014 to 2023). "Of note, two patients, one of whom carried the FABP3 frameshift mutation (c.395delA) and one with the FABP7 frameshift mutation (c.239delA), suffered from hyperlipidemia." (PMID 25027319, 2014). "the female patients had a longer duration of schizophrenia; higher levels of hyperlipidemia, total cholesterol, HDL-C, eGFR, and FABP3, and lower levels of uric acid, creatinine, albumin, hematocrit, hemoglobin, and high-sensitivity CRP, white blood cell count and were older than the male patients." (PMID 37255976, 2023).
brain injury (5 papers, 2009 to 2025). Acute and chronic (see also brain INJURIES, CHRONIC) injuries to the brain, including the cerebral hemispheres, CEREBELLUM, and brain STEM. "Furthermore, a recent study demonstrated that FABP3 is an early outcome predictor in patients with traumatic brain injury." (PMID 37277809, 2023). "Conversely, fatty acid-binding proteins (FABP1, FABP3, FABP4, FABP7) decreased over time in uninjured infants but increased in those with brain injury, suggesting a role in exacerbating damage." (PMID 40924950, 2025).
cognitive decline (5 papers, 2021 to 2023). "Furthermore, a negative correlation between FABP3 and the Mini-Mental State Examination (MMSE) has also been recently demonstrated in the early stages of AD, underlining that FABP3 could be an early predictor of cognitive decline." (PMID 36358488, 2022). "Correlation analyses revealed significant associations between FABP3 and established biomarkers with MMSE scores, indicating a potential link between FABP3 levels and cognitive decline." (PMID 37686075, 2023). "Second, our data also indicate that blood-based FABP-3 may have prognostic potential as it predicted future cognitive decline beyond standard CSF AD biomarkers." (PMID 36631909, 2023). "In addition, αSyn levels of higher molecular weight and insoluble species should also be investigated in the MS/DB in this model and the relevance of FABP3 in order to further highlight the importance of αSyn pathology in the region for cognitive decline." (PMID 33401521, 2021). "We suggest that FABP3 play a pivotal role in the development of cognitive decline." (PMID 34300173, 2021). "In contrast, FABP-3 did not relate to cognition at baseline, but higher baseline FABP-3 was indicative of cognitive decline at follow-up." (PMID 36631909, 2023). "Since we have demonstrated that fatty acid-binding protein 3 (FABP3) is critical for αSyn neurotoxicity in nigral dopaminergic neurons, we investigated whether FABP3 also participates in αSyn pathology in the MS/DB and cognitive decline." (PMID 33401521, 2021). "Our study has shown significantly increased FABP3 concentrations in CSF of AD patients compared to MCI subjects and older people without cognitive decline." (PMID 34300173, 2021).
embryonic cancer (5 papers, 2015 to 2025). "The mechanisms of FABP3 in cancer include the following: mitochondrial dysfunction and cell apoptosis: Overexpression of FABP3 in embryonic cancer cells leads to reduced mitochondrial membrane potential, decreased ATP synthesis, and increased oxidative stress, ultimately inducing cell apoptosis." (PMID 40717587, 2025). "Furthermore, depletion of Fatty acid binding protein 3 (FABP3) enhanced ROS production in P19 embryonic carcinoma cells." (PMID 26416514, 2015).
glioma (5 papers, 2017 to 2023). A benign or malignant brain and spinal cord tumor that arises from glial cells (astrocytes, oligodendrocytes, ependymal cells). "Other fatty acid-binding proteins such as FABP3, FABP5, FABP6 and FABP7 have been also implicated in glioma migration or invasion." (PMID 37120445, 2023). "We recently identified mammary‐derived growth inhibitor (MDGI/FABP3) as a biomarker for invasive gliomas." (PMID 31068339, 2019). "The Harris group, however, demonstrated that hypoxia-induced-lipid storage in breast and glioma cell lines is due to a HIF-dependent increase in fatty acid uptake via transcriptional regulation of fatty acid-binding proteins FABP3 and FABP729." (PMID 29176561, 2017). "Yet, three of them, FABP3, RGS16, and EBF2, are relevant for glioma biology." (PMID 35563134, 2022). "Interestingly, FABP3 and RGS16 have been proposed as markers of invasive glioma, and EBF2 positively regulates neuronal migration." (PMID 35563134, 2022).
Hepatic steatosis (5 papers, 2015 to 2025). Steatosis is a term used to denote lipid accumulation within hepatocytes. "Recent study has suggested that FABP3 is upregulated in hepatic steatosis in zebrafish model, and hepatic steatosis can be ameliorated by suppressing FABP3 expression in the liver." (PMID 31828095, 2019). "Furthermore, hesperidin, a citrus bioflavonoid, ameliorated liver steatosis in high-cholesterol diet rats through FABP3 down regulation in the liver." (PMID 26052340, 2015). "Thus we hypothesized that E2F8 transcription factor mediated FABP3 transactivation might be a downstream of PPARα in the development of hepatic steatosis." (PMID 26052340, 2015). "Also, we demonstrated that celastrol inhibited the transcriptional activity of PPARγ, thereby decreasing the Fabp3, Fatp1, MCAD, Fads2, and ACC1 mRNA expression in OA-induced hepatic steatosis cells." (PMID 38276299, 2024).
lung adenocarcinoma (5 papers, 2023 to 2024). A carcinoma that arises from the lung and is characterized by the presence of malignant glandular epithelial cells. "The FABP3 facilitates the AA transport and its reaction with taurine, resulting in reduced overall AA levels and lipid peroxidation and desensitization of lung adenocarcinoma cells to ferroptosis." (PMID 38594265, 2024). "Lung adenocarcinoma (LUAD)-derived exosomal circRNA_101093 (cir93) increases fatty acid-binding protein 3 (FABP3) to reduce global arachidonic acid through reactions with taurine, thus inducing ferroptosis by desensitizing LUAD cells and decreasing total lipid peroxidation." (PMID 38216595, 2024). "In lung adenocarcinoma (LUAD), exosomal circRNA_101093 from LAC cells upregulated expression of FABP3 protein and desensitize LUAD cells to ferroptosis via a FABP3-dependent reduction." (PMID 37213665, 2023). "Additionally, researchers found that exosomal circRNA_101093 (cir93) could bind to fatty acid-binding protein 3 (FABP3) and increase its expression, desensitizing lung adenocarcinoma cells to ferroptosis." (PMID 38177102, 2024).
non-small cell lung carcinoma (5 papers, 2018 to 2025). A group of at least three distinct histological types of lung cancer, including non-small cell squamous cell carcinoma, adenocarcinoma, and large cell carcinoma. "It was also reported that the expression of FABP3 was significantly increased in tumor mass compared to adjacent mass in non-small-cell lung cancer and higher expression of FABP3 was an independent prognostic factor in non-small-cell lung cancer." (PMID 36478991, 2022). "Moreover, in non-small cell lung cancer and gastrointestinal stromal tumors, FABP3 overexpression is notably correlated with tumor size and lymph node metastasis of advanced tumors and with remarkably shorter survival of patients." (PMID 35356506, 2022). "High expression of FABP3 or FABP4 in non-small cell lung cancer (NSCLC) was significantly associated with advanced tumor node metastasis stage and had a negative impact on the overall survival of NSCLC patients." (PMID 30242145, 2018).
Anxiety (4 papers, 2014 to 2025). Intense feelings of nervousness, tension, or panic often arise in response to interpersonal stresses. "For instance, FABP3 knockout mice exhibit reduced social memory and novelty-seeking behaviors, while FABP7 knockout mice exhibit hyperactivity and anxiety-related phenotypes." (PMID 40362160, 2025). "The Fabp3 knockout (KO) mice showed decreased social memory and novelty seeking, and Fabp7 KO mice displayed hyperactive and anxiety-related phenotypes, while Fabp5 KO mice showed no apparent phenotypes." (PMID 25027319, 2014).
Arrhythmia (4 papers, 2020 to 2022). Any cardiac rhythm other than the normal sinus rhythm. "Therefore, assessing FABP3 could provide useful information in patients with arrhythmia." (PMID 33850478, 2021).
Cerebral ischemia (4 papers, 2013 to 2026). Restriction of arterial blood supply to the brain associated with insufficient oxygenation to support the metabolic requirements of the tissue. "Collectively, our findings suggest that FABP3 is an important promoter of cerebral ischemia-reperfusion injury." (PMID 42274596, 2026). "In summary, the present study suggested that increased FABP3, FABP5 and FABP7 expression in the brain is a novel biochemical marker of cerebral ischemia and that the FABP inhibitor, MF6 inhibited their expression levels to play a neuroprotective role in cerebral I/R in mice." (PMID 34068550, 2021).
Creutzfeldt-Jakob disease (4 papers, 2012 to 2023). "FABP3 is considered as a promising and sensitive marker for minor brian injury and Creutzfeldt-Jakob disease." (PMID 28222113, 2017). "Previous studies showed a significant increase of FABP3 in CSF of AD patients, as well as in other neurodegenerative disorders, including Creutzfeldt-Jacob disease (CJD), vascular dementia (VAD), and Dementia with Lewy Bodies (DLB), while no data were available for FTD patients before our work." (PMID 37454217, 2023).
melanoma (4 papers, 2019 to 2025). A malignant, usually aggressive tumor composed of atypical, neoplastic melanocytes. "Interestingly, some proteins that bind and process lipids, including phospholipase D3 (PLD3), inositol triphosphate protein kinase B (ITPKB), inositol triphosphate receptor 3 (ITPR3), fatty acid binding protein 3 (FABP3), have been found strongly upregulated in melanoma." (PMID 32528879, 2020).